APLN (apelin)
Diseases named in the same sentence as APLN in open-access papers (continued):
Sharing a sentence is not in itself a finding about the gene and the disease.
atherosclerosis (58 papers, 2011 to 2026). A disease characterized by the build-up of fatty material and calcium deposition in the arterial wall resulting in partial or complete occlusion of the arterial lumen. "Apelin/APJ has been demonstrated to be involved in the development of hypercholesterolemia-associated atherosclerosis similarly to angiotensin II/AT1, which promotes endothelial dysfunction and myosin light chain phosphorylation in VSMCs." (PMID 36902176, 2023). "Apelin-13 has been implicated in atherosclerosis in several studies on account of its immunoreactivity in human aortas and coronary arteries." (PMID 36034795, 2022). "In an Apo E-deficient atherosclerosis model apelin treatment mitigated native and Ang II-accelerated atherosclerosis by promoting nitric oxide (NO) production." (PMID 34640437, 2021). "In the present study, we also investigated serum homocysteine levels and carotid IMT in patients with SCH and the association of serum irisin and apelin levels with these markers of atherosclerosis." (PMID 30864627, 2019). "For instance, administration of apelin blocks a spectrum of AngII-mediated effects on atherosclerosis in the apolipoprotein E-deficient mice through the formation of a heterodimer between the apelin and AngII receptors." (PMID 26342945, 2015). "Apelin/APJ deficiency is preventative against oxidative stress-linked atherosclerosis, and the apelin/APJ system works as a mediator of oxidative stress in vascular tissue." (PMID 23554778, 2012). "However, in ApoE-deficient mice, apelin infusion inhibited atherogenesis and completely abrogated angiotensin II-accelerated atherosclerosis." (PMID 29070519, 2017). "Several studies also showed that the APJ receptor and apelin were associated with atherosclerosis." (PMID 25993436, 2015). "In high-fat-diet-treated Apoe-/- mice, the loss of apelin results in exacerbation of atherosclerosis, while apelin administration leads to a significant regression of atherosclerosis, which may be related to the activation of the nitric oxide pathway and inhibition of Ang II signaling." (PMID 35355561, 2022). "In an earlier study, the authors suggest that the apelin level is related to enhanced serum lipids and can be used as a predictor of atherosclerosis in diabetic patients." (PMID 40299338, 2025). "Some myokines such as fibroblast growth factor 21, musclin, and apelin have a salutary effect on the cardiovascular system, which is related to protection against atherosclerosis and blood pressure control." (PMID 40594910, 2025). "It is assumed that the apelin (AP) and Elabela (Ela) peptides included in the apelinergic system play a role as mediators of the endothelial function and atherosclerosis." (PMID 40299338, 2025). "In contrast, Apelin has a positive effect by decreasing angiotensin II, thereby reducing atherosclerosis." (PMID 36980823, 2023). "Nevertheless, our results clearly indicate that apelin promotes SMC dedifferentiation towards a synthetic phenotype characteristic of atherosclerosis development." (PMID 37907514, 2023). "A concomitant decrease in mitochondrial fusion has been reported: in atherosclerosis development, apelin-13 promotes the downregulation of MFNs and OPA1." (PMID 36834825, 2023). "The same group found that apelin 13 accelerated atherosclerosis in the aorta, while the pharmacological inhibition of DRP1 restored the physiological mechanism of fission and attenuated the proliferating activity of VSMCs in APOE−/− mice." (PMID 36834825, 2023). "Accordingly, apelin is related to enhanced serum lipids and can be utilized as a predictor of premature atherosclerosis in T1DM patients." (PMID 35913970, 2022). "A recent study showed that the apelin/APJ system is involved in the development of atherosclerosis by influencing vascular smooth muscle cells." (PMID 36034795, 2022).
atherosclerosis (continued). "However, the most important role of apelin in RA individuals seems to be related to the prediction of RA patients’ cardiovascular risk, insofar as apelin, along with the inflammation of RA, can be used to predict atherosclerosis development and atheroma plaque stability in RA patients." (PMID 35682868, 2022). "Apelin was shown to attenuate the progression of atherosclerosis by promoting cholesterol efflux and reducing foam cell formation." (PMID 34640437, 2021). "F13A acts as an antagonist of apelin-13 in PINK1 and Parkin-dependent mitophagy, which suppresses the apelin-13 influence in the atherosclerosis development." (PMID 33669743, 2021). "Additionally, pathways implicated in atherosclerosis comprised fluid shear stress and atherosclerosis, lipid and atherosclerosis and apelin signaling." (PMID 41323198, 2026). "Notably, pathways such as PI3K-Akt, MAPK, insulin, prolactin, ErB, apelin and lipid and atherosclerosis signaling are involved in glucose metabolism, protein synthesis, and energy metabolism." (PMID 41282288, 2025). "The discrepancy between those results might be due to a different impact of apelin on early atherosclerosis development versus late-established plaque development; the pleiotropic functions of the apelin/APJ system depend on cell type, tissue, and disease." (PMID 41155377, 2025). "The higher level of Apelin may have a valuable or adverse impact on the progression of atherosclerosis." (PMID 36980823, 2023). "A close relationship between apelin and atherosclerosis has been demonstrated." (PMID 37907514, 2023). "However, apelin’s ability to abrogate the development of atherosclerosis by increasing NO bioavailability and antagonizing angiotensin II cellular signaling was also described." (PMID 36902176, 2023). "In addition, several extensively researched cancer-related pathways were identified as risk-active pathways in multiple cancers such as the lipid and atherosclerosis pathway, Apelin signaling pathway, Hippo signaling pathway, and Wnt signaling pathway." (PMID 36980844, 2023). "It was previously reported that Apelin signaling may serve as a key atherosclerosis-protective marker to control the onset of CHD." (PMID 36980823, 2023). "Likewise, the activated Apelin signaling pathway facilitated atherosclerosis by promoting oxidative stress in the vascular environment, resulting in the deposition of oxidized lipids and eventually endothelial damage." (PMID 36980823, 2023). "In addition, the PI3K-Akt signaling pathway, cellular senescence, the apelin signaling pathway, fluid shear stress and atherosclerosis were enriched in the sALS samples." (PMID 36707813, 2023). "The lower apelin levels may also contribute to the other comorbidities of hypothyroidism, e.g., accelerated atherosclerosis." (PMID 36187132, 2022). "In addition, vaspin, apelin and omentin-1 exert protective effects on atherosclerosis by inhibiting ROS generation, enhancing cholesterol efflux and reducing activation of inflammatory macrophages, respectively." (PMID 30305178, 2018). "Angiotensin had been proved to be an atherosclerosis inducer, so it is hypothesized that apelin is also a critical factor in the progress of atherosclerosis." (PMID 29302260, 2017). "Apelin also plays an important role in atherosclerosis development in mice." (PMID 26342945, 2015). "Furthermore, novel adipokines, such as visfatin, apelin, and vaspin, have emerged as potential mediators of the interplay between MS and atherosclerosis in HIV-infected patients." (PMID 22203832, 2012). "From the pathophysiological point of view, it might be speculated that apelin acts as a vasopressor in damaged vasculature (e.g., atherosclerosis) and plasma apelin levels may be a useful indicator for the severity of coronary artery stenosis." (PMID 23554778, 2012).
atherosclerosis (continued). "Moreover, based on KEGG pathway analysis, several other T2DM-CAD-related processes, including leukocyte transendothelial migration, fluid shear stress and atherosclerosis, focal adhesion, along with apelin, Wnt, and chemokine signaling pathways, were found to enrich Hub II genes." (PMID 39080630, 2024). "The discrepancy between the different results might be attributed to the different models used, the impact of apelin on early atherosclerosis development versus late established plaque development, and the pleiotropic functions of the apelin/APJ system depending on cell type, tissue and disease." (PMID 37907514, 2023). "Based on our previous data that ACE2 is diminished on CKD leukocytes and monocytes, and that the APLN/APNR-axis may be related to atherosclerosis and inflammation, we aimed to investigate the correlation between serum-APLN, leucocytic APLNR, and ACE2 expression in CKD patients." (PMID 33255902, 2020). "In ApoE-knockout mice infused with angiotensin II to induce atherosclerosis of the coronary arteries, coinfusion of apelin-13 could activate nitric oxide and thereby attenuate atherosclerosis of these vessels, as well as prevent vascular remodeling in a vein graft model." (PMID 31492821, 2019). "Apelin exerts acute anti-inflammatory effects on the vascular system; the results are promising and if these results can be extrapolated in chronic models, it can be a proper therapeutic modality for prevention of inflammation in the process of atherosclerosis." (PMID 22655211, 2012). "In atherosclerosis, apelin might have beneficial effects, as apelin has been shown to stimulate endothelial NO production and antagonize the Ang II-induced formation of atherosclerotic lesions and aortic aneurysms in a murine model of atherosclerosis." (PMID 21410966, 2011). "The KEGG pathway analysis identified significant enrichment in pathways related to fluid shear stress and atherosclerosis, the MAPK signaling pathway, the Apelin signaling pathway, and the cell cycle." (PMID 41150767, 2025). "Up-regulation of has_circ_0126672 affected various CHD-related cellular functions, such as atherosclerosis, JAK/STAT, and Apelin signaling pathways." (PMID 36980823, 2023). "Additionally, in an animal ex vivo study, Cardoso dos Santos found that apelin promotes VSMC dedifferentiation from a contractile/differentiated towards a synthetic phenotype, a process characteristic of atherosclerosis development." (PMID 41155377, 2025). "Apelin-13 induces VSMC proliferation via Cyclin D 1 and migration through matrix metalloproteinase (MMP)-2 activation, both considered critical processes in the pathogenesis of atherosclerosis." (PMID 41155377, 2025). "In AS, apelin-13 increases mitophagy by activating the PINK1/Parkin pathway, and F13A is an apelin-13 antagonist in PINK1 and Parkin-dependent mitophagy, which blocks the effect of apelin-13 in the progression of atherosclerosis." (PMID 32257551, 2020). "Although it is clear that apelin is an important factor for AS, it is still difficult to define whether apelin/APJ has a beneficial or harmful role in atherosclerosis." (PMID 29302260, 2017). "Due to lack of data and contradictory findings, the exact role of apelin on atherosclerosis plaque remains inconclusive." (PMID 22655211, 2012). "Apelin-13 downregulates the expression of lipoprotein lipase through the AOJ/PKCα/miR-361-5p signaling pathway in macrophage-derived foam cells, leading to inhibition of lipid accumulation and pro-inflammatory cytokine secretion and as a result, alleviating the atherosclerosis." (PMID 41155377, 2025). "It is postulated that apelin may play a role in atherosclerosis, but the mechanism has not yet been discovered." (PMID 40943120, 2025).
atherosclerosis (continued). "Thus, it will be important to decipher the complex relationship between apelin and S100A4, the mechanisms leading to apelin nuclear hijack and whether it might constitute a potential target in toning down SMC-driven atherosclerosis development." (PMID 37907514, 2023). "The role apelin plays in the pathogenesis of atherosclerosis has not been fully defined." (PMID 37956047, 2023).
myocardial infarction (48 papers, 2012 to 2026). Gross necrosis of the myocardium, as a result of interruption of the blood supply to the area, as in coronary thrombosis. "Of interest, a complete loss of apelin—an endogenous ligand of Aplnr—results in increased mortality of mice with myocardial infarction, paralleled by increase in infarct size and inflammation." (PMID 37762130, 2023). "Apelin reduces myocardial damage caused by myocardial infarction." (PMID 36199867, 2022). "Interestingly, the loss of apelin in apelin-knockout mice increased myocardial infarction mortality, infarct size, and inflammation, with a reduction of the prosurvival pathway via phosphatidyl inositol 3-kinase/protein kinase B (PI3K/Akt)." (PMID 29875677, 2018). "Apelin deficiency worsened outcome in myocardial infarction and ischaemia–reperfusion injury." (PMID 26143239, 2015). "This study explores the role of the C-type natriuretic peptide (CNP) system in myocardial infarction (MI) and its modulation by Apelin-13 functionalized patches (A-13p)." (PMID 41751165, 2026). "Expression of apelin and the APJ receptor increases under hypoxic conditions associated with myocardial infarction." (PMID 41155377, 2025). "The major strength of the study was the measurement of serum concentrations of the novel apelin axis peptides in humans in the scenario of myocardial infarction." (PMID 38137673, 2023). "Myocardial infarction resulted in an increase in apelin and apelin receptor expression by about 2-fold." (PMID 36986889, 2023). "In a mouse model of myocardial infarction (MI), cardiac LECs involved in reparative lymphangiogenesis have been shown to express apelin and its receptor after ischemic injury, while nearby dormant lymphatic vessels do not." (PMID 38178871, 2023). "In post-myocardial infarction diabetic mice, the overexpression of apelin markedly upregulates SIRT3 and angiogenic growth factor expression." (PMID 35355561, 2022). "In a pathological setting of myocardial infarction, the bioactive peptide apelin enhances the secretion of S1P in lymphatic endothelial cells, by modulating the expression of Spns2 and SphK2." (PMID 34572307, 2021). "Administration of apelin or apelin analogs in rodents post-myocardial infarction improved functional recovery and reduced infarct size, most likely due to increase NO production and angiogenesis." (PMID 34880830, 2021). "Using animal models, some research observed that exogenous APLN treatment reduced infarct size and simultaneously increased heart rate while apelin-knockout mice are characterized by increased myocardial infarction size and mortality." (PMID 33171610, 2020). "The findings of other studies have demonstrated efficiency of myocardial protection induced by apelin limiting myocardial infarction and its action as a regulatory peptide increasing cadiac contractility." (PMID 28728608, 2017). "Myocardial injection of apelin-overexpressing bone marrow cells improves cardiac repair via upregulation of Sirt3 after myocardial infarction." (PMID 26342945, 2015). "In apelin knockouts, following acute myocardial infarction infarct size and mortality were increased, and with carotid ligation neointimal lesion area was reduced." (PMID 26143239, 2015). "Mouse myocardial infarction was achieved by coronary artery ligation and BMCs overexpressing apelin (apelin-BMCs) or GFP (GFP-BMCs) were injected into ischemic area immediately after surgery." (PMID 24039710, 2013). "Our previous study shows that treatment with apelin increases bone marrow cells (BMCs) recruitment and promotes cardiac repair after myocardial infarction (MI)." (PMID 24039710, 2013). "What is important in the context of our study is that apelin also significantly improves cardiac function and repair after myocardial infarction by increasing angiogenesis, stromal cell-derived factor-1α, chemokine receptor 4 (CXCR-4) and homing of vascular progenitor cells." (PMID 41198895, 2025).
myocardial infarction (continued). "This direct protection against myocardial ischemic injuries by Apelin-13 may also be, at least in part, conducive to promoting the recovery of cardiac function in mice after myocardial infarction." (PMID 40104400, 2025). "In myocardial infarction apelin and apelin receptor, both expressed on human platelets, may play a role in reducing platelet aggregation by NO-cyclic guanosine monophosphate signaling." (PMID 40943120, 2025). "Previous studies have shown that circulating levels of apelin were sufficiently lower in patients with established cardiovascular diseases (coronary artery disease, myocardial infarction, acute coronary syndrome, HF), T2DM, and obesity than in healthy volunteers." (PMID 37239123, 2023). "Furthermore, apelin inhibits apoptosis, decreases myocardial infarction size, and prevents myocardial ischemia/reperfusion injury via the PI3K/Akt and ERK1/2 caspase signaling." (PMID 37239123, 2023). "Furthermore, in post-myocardial infarction diabetic mice, the overexpression of apelin mobilizes endothelial progenitor cells to ischemic regions and contributes to angiogenesis." (PMID 35355561, 2022). "Notably, the apelin/APJ system promotes the expression of myocardial infarction (MI) indicator protein, which leads to increased angiogenesis and improves cardiac repair post-MI by inhibiting apoptosis." (PMID 36611944, 2022). "However, above all, APLN has a protective role in heart failure, including acute pathologies like myocardial infarct and chronic heart disorders, such as cardiac hypertrophy." (PMID 33171610, 2020). "All of these results, suggest that apelin could be responsible for increased cardiac output and cardioprotective effect against myocardial infarction and oxidative stress." (PMID 29875677, 2018). "In failing human heart, apelin has a cardioprotective effect against myocardial infarction." (PMID 29875677, 2018). "Because myocardial angiogenesis plays an important role in cardiac function in cardiac atherosclerotic diseases, the positive effect of apelin indicates that it could be used as a myocardial protecting factor after myocardial infarction." (PMID 29302260, 2017). "Regarding the mechanism for apelin-13 promoting angiogenesis after myocardial infarction, studies explored that apelin could upregulate the expression of SDF-1a/CXCR-4 and the homing of vascular progenitor cells." (PMID 29302260, 2017). "A substantial body of evidence supports the concept that apelin could prevent cardiovascular remodeling induced by myocardial infarction or by pressure overload in mice or rats through different mechanisms." (PMID 26342945, 2015). "Understanding the role of apelin may have relevance to future preventive and/or therapeutic strategies for myocardial infarction." (PMID 25634182, 2015). "Myocardial infarct could affect apelin and apelin receptor expression in the heart." (PMID 36986889, 2023). "Moreover, [Pyr1]apelin-13 injection into a rat model of myocardial infarction resulted in decreased infarct size, and increased heart rate and serum nitric oxide level in consecutive days, indicating that apelin has a sustained cardioprotective effect against myocardial infarction." (PMID 29875677, 2018). "Apelin gene therapy has demonstrated significant improvements in the densities of capillaries and arterioles, and alleviating cardiomyopathy and myocardial infarction (MI) in the hearts of diabetic mice." (PMID 37237500, 2023). "Six studies reported circulating apelin changes in CAD patients, 4 studies in acute coronary syndrome (ACS) patients and 3 studies in acute myocardial infarction (AMI) patients." (PMID 28915675, 2017). "Further studies are needed to verify the effect of Apelin-13 in animal models exploring its potential therapeutic effect in pathological conditions such as myocardial infarction, with or without the injection of stem cells." (PMID 36361860, 2022).